DPP4 (dipeptidyl peptidase 4)
Diseases named in the same sentence as DPP4 in open-access papers (continued):
Sharing a sentence is not in itself a finding about the gene and the disease.
COVID-19 (continued). "Therefore, the potent anti-inflammatory effect of diabetic pharmacotherapies such as metformin, pioglitazone, sodium-glucose co-transporter-2 inhibitors (SGLT2Is), and dipeptidyl peptidase-4 (DPP4) inhibitors may mitigate the COVID-19 severity." (PMID 34124187, 2021). "Therefore, the potent anti-inflammatory effect of diabetic pharmacotherapies such as metformin, pioglitazone, sodium-glucose co-transporter-2 inhibitors (SGLT2Is), and dipeptidyl peptidase-4 (DPP4) inhibitors may mitigate COVID-19 severity." (PMID 34124187, 2021). "Thus, the use of DPP4 peptide may represent an innovative approach to be employed for the pharmacologic treatment of COVID-19." (PMID 34452531, 2021). "Therefore, the use of DPP4 inhibitors (gliptins) in COVID-19 management should be better exploited to improve the overall knowledge on how DPP4 may be useful to design novel therapies to block SARS-CoV-2 entry." (PMID 34307267, 2021). "Dipeptidyl peptidase-4 (DPP-4) inhibitor has anti-inflammatory, anti-fibrotic, and anti-adipogenic characteristics, which could be effective in inhibiting the progression to hyper-inflammation in extreme cases of COVID-19." (PMID 35822018, 2021). "The broad expression of DPP4 might explain the vast range of COVID-19 symptoms." (PMID 35822018, 2021). "High expression of DPP4 may associate with elevated morbidity of COVID-19 and poor prognosis in LUSC patients, indicating that intensive care is needed for these patients during COVID-19 epidemic." (PMID 33614513, 2021). "For this reason, it has been hypothesized that DPP4 inhibitors, known as gliptins, which vary in their interactions with the active site of the enzyme, may have immunomodulatory and cardioprotective beneficial effects in COVID-19 management." (PMID 33050220, 2020). "To the best of our knowledge, we are the first to hypothesize that DPP-4 inhibitors might emerge as a valuable asset in the alleviation of COVID-19 long-term repercussions following patients’ recovery, given their favorable effects in protection and tissue regeneration." (PMID 32848788, 2020). "Thus, the DPP-4 pathway poses an intriguing possibility for novel COVID-19 therapeutics." (PMID 33318519, 2020). "Therefore, we suggest that similar to the case for ACE2, DPP4 upregulation may be adeterminant of COVID-19 progression and prognosis." (PMID 33269102, 2020). "Of note, DPP4 inhibitors exert anti-inflammatory effects without increasing the risk of infectious disease and thus may prove protective against COVID-19-induced lung injury." (PMID 33195481, 2020). "However, gliptins do not bind to the suggested binding site of SARS-CoV-2, meaning that the wealth of data surrounding DPP4 may serve a basis for the development of new drugs, as opposed to a direct repurposing of DPP4i for treatment of COVID-19." (PMID 32838195, 2020). "DPP4 also plays a role in immune regulation by activating T cells, and is purported to increase inflammation in diabetic patients In the case of COVID-19, diabetes has been suggested to modulate the host-viral interactions and contribute to ineffective host immune responses." (PMID 32719619, 2020). "Additionally, DPP4 dysregulation has been seen in COVID-19 patients." (PMID 33510644, 2020). "Therefore, in case it is demonstarted that SARS-CoV-2 can bind DPP4, exogenous acute administration of sDPP4 as a decoy factor to compete for binding of the virus to endogenous DPP4 in COVID-19 target tissues could be explored." (PMID 32848769, 2020). "However, despite a plausible pharmacological rationale, validation of drugs with originally different therapeutic indications for preventing or treating COVID-19 can be challenging even in the case of DPP4 inhibitors, as current computational or preclinical evidence does not suffice." (PMID 32456064, 2020).
COVID-19 (continued). "However, a comparison of safety signals associated with the use of DPP-4 inhibitors across the years showed an upward trend in adverse event signals, showing an increase in ROR, PPR, and EBGM values, especially in the post-COVID-19 pandemic compared to previous years." (PMID 40006028, 2025). "Additionally, narrative reviews have proposed plausible non-glycemic mechanisms, including inhibition of viral entry, anti-inflammatory effects, and attenuation of fibrotic pathways, through which DPP-4 inhibitors might influence the COVID-19 disease course beyond glycemic control." (PMID 40869643, 2025). "However, NRP1 and DPP4 may have opposing roles in COVID-19 pathogenesis." (PMID 40431631, 2025). "The results showed that rutin exhibited a strong inhibitory effect on FXR/RXR, DPP4, JAK2, and ACE, suggesting its potential as a therapeutic agent for modulating these COVID-19-related targets." (PMID 40076279, 2025). "The results demonstrated that high doses of isochlorogenic acid C inhibited FXR/RXR, DPP4, JAK2, ACE, CNGA1, BLT1, COX-2, and 5-LOX, suggesting its potential to modulate COVID-19-related inflammatory pathways." (PMID 40076279, 2025). "Among these inflammatory mediators, we identified known markers of severe COVID-19, such as the monocyte-recruiting chemokine CXCL10 and DPP4." (PMID 39334742, 2024). "Two known markers of severe COVID-19 were identified among the soluble mediators modulated during Sulfodyne® treatment, CXCL10, and DPP4." (PMID 39334742, 2024). "The early phase in SARS-CoV-2 infection is the link between the COVID-19 virus and the host cell receptors, consisting of angiotensin-converting enzyme 2 (ACE2) and the dipeptidyl peptidase-4 (DPP4) receptor." (PMID 37299603, 2023). "Through network analysis, it was found that the core targets of GGQL in the treatment of COVID-19 comorbid with DM include AR, GSK3B, DPP4, F2, NOS3, and so on." (PMID 37933071, 2023). "DPP-4 inhibitors (DPP-4i) are a class of anti-hyperglycemic drugs used for the treatment of type-2 diabetes (T2D) and can better repurposing drug for COVID-19 patients." (PMID 36776226, 2023). "The present study aims to update the use of novel antidiabetic molecules (DPP4-i, GLP-1 Ra, SGLT2-i) in T2DM and COVID-19 patients by highlighting primary and secondary outcomes from clinical studies and underlying possible molecular mechanisms." (PMID 36289885, 2022). "However, the sample size in the first study was particularly low, and despite that the latter study found a similar gradual decrease in DPP4 protein concentration with increasing disease severity none of these studies reported any association with COVID-19 mortality." (PMID 35195023, 2022). "Network pharmacology analyses identified 6 potential targets (IL6, DPP4, MIF, PRF1, SERPING1, and SLC6A4) for emetine in anti-LUAD/COVID-19." (PMID 35733175, 2022). "On one side some studies highlight the finding that the S1 domain of the COVID-19 spike glycoprotein potentially interacts with the human CD26, indicating DPP4 as one of the functional receptor of the human coronavirus." (PMID 35406799, 2022). "In COVID-19 patients with T2DM, the use of DPP4 inhibitors reduced odds of clinical deterioration and hyperinflammatory syndrome." (PMID 36009573, 2022). "Thus, it is conceivable that pre-existing upregulation of DPP4 increased susceptibility to post-COVID-19 syndrome via increased viral entry (i.e., reverse causation), rather than DPP4 upregulation occurring in response to COVID-19." (PMID 35151371, 2022). "The dynamics of the connection between DPP4/CD26 localization and site inflammation of the lungs, due to COVID-19, appeared to be verified." (PMID 35406799, 2022). "In addition, gliptins reduce macrophage infiltration to the kidney and ameliorate early renal injury, which indicates that DPP4 inhibitors might be a therapeutic approach to preserve renal function since renal failure is a quite common complication in COVID-19 patients." (PMID 36009573, 2022).
COVID-19 (continued). "Thus, DPP4 inhibitors or ACE2 activators could reverse early AKI in COVID-19." (PMID 34629845, 2021). "In April 2020, we published an article in CellR4 highlighting the possible therapeutic role of DPP-4 and DPP-4i in COVID-19 pathophysiology." (PMID 33906375, 2021). "Therefore, DPP4 inhibition may hinder the infection and/or development of the COVID-19." (PMID 34068970, 2021). "We find the gut as the putative hotspot of COVID-19, where a maturation correlated transcriptional signature is shared in small intestine enterocytes among coronavirus receptors (ACE2, DPP4, ANPEP)." (PMID 32463365, 2020). "It has also been hypothesized that human dipeptidyl peptidase 4 (DPP4) could be a functional receptor for the S protein of SARS-CoV-2, which in turn led to the hypothesis that DPP4 inhibitors may play a role in preventing and reducing the risk and progression of COVID-19." (PMID 33240091, 2020). "Interestingly, DPP4 inhibitors were introduced as 2nd to 4th-line treatment option of type 2 diabetes, and they might be a suitable combinatory treatment option for COVID-19 patients." (PMID 32806722, 2020). "Additionally, the wide expression of DPP4 could explain the variety of symptoms of COVID-19." (PMID 33510644, 2020). "Conversely, anxiety may impact the function of five COVID-19 regulators, including the activation of four proteins (IL6, angiotensin 2, TNF, and IL10) and the inhibition of one protein (DPP4)." (PMID 40766923, 2025). "Dipeptidyl peptidase-4 (DPP-4) inhibitors, widely used antidiabetic agents, are hypothesized to affect COVID-19 outcomes via anti-inflammatory and immune-modulating mechanisms." (PMID 40869643, 2025). "Accordingly, the use of DPP-4 inhibitors in patients with COVID-19, either diabetic or not, can simply decrease the entry and replication of SARS-CoV-2 in the lungs." (PMID 39526061, 2024). "In fact, there are several studies indicating the positive impact of application of DPP4 inhibitors in therapy on the clinical outcomes of both diabetic and non-diabetic patients with COVID-19." (PMID 39273582, 2024). "This at least suggests that anti-diabetic DPP-4 inhibitor drugs are not harmful in COVID-19 patients." (PMID 37064327, 2023). "Although this report does not prove that DPP-4 inhibitors directly reduce the severity of COVID-19, it presents a possible treatment strategy worth investigating further." (PMID 37064327, 2023). "In addition, this study shows the role of dipeptidyl peptidase 4 (DPP-4) as a potential receptor for SARS-CoV-2 and the effectiveness of DPP-4 inhibitors in facing COVID-19." (PMID 37789314, 2023). "The top 5 targets were AR (degree = 93), GSK3B (degree = 70), DPP4 (degree = 52), F2 (degree = 43) and NOS3 (degree = 34), and their candidate targets may be the main targets of GGQL against COVID-19 comorbid with DM." (PMID 37933071, 2023). "Another population-based study showed that out of 832 diabetic patients with novel coronavirus disease, the 263 patients who were taking DPP-4 inhibitors showed 64% less severe symptoms of COVID-19 than non-users." (PMID 37064327, 2023). "Of note, several other studies, mainly retrospective cohorts and subsequent meta-analysis, suggest no harm or benefit of DPP4 inhibitors administration in T2D COVID-19 patients." (PMID 37374918, 2023). "In both diabetic and non-diabetic subjects, DPP-4 inhibitors have been demonstrated to reduce blood pressure and hypertension, another common occurrence in COVID-19 patients." (PMID 37064327, 2023). "It is hypothesized that DPP-4 levels are dysregulated in patients with T2DM, which may have a negative vascular impact, hence leading to increased severity of COVID-19." (PMID 36289885, 2022). "Furthermore, sitagliptin, through the inhibition of DPP4, increases circulating levels of glucagon-like peptide-1 (GLP-1), which has been shown to reduce inflammatory changes in COVID-19." (PMID 36355535, 2022).
COVID-19 (continued). "DPP4, also known as cluster of differentiation 26 (CD26), is the receptor of Middle East Respiratory Syndrome Coronavirus (MERS-CoV) and has been recently proposed as a potential drug target for COVID-19." (PMID 35305698, 2022). "Meanwhile, the presence of memory B cells in the BAL was linked to increased DPP4 (but not LDH) and a range of pathophysiological outcomes post-COVID-19." (PMID 35151371, 2022). "They found that circulating DPP4 activity is decreased in the serum of hospitalized patients with acute COVID-19 in comparison with that of patients recovered from acute COVID-19 or those who were never exposed to SARS-CoV-2." (PMID 35195023, 2022). "In addition, we evaluated the potential bindings of emetine with the LUAD/COVID-19 targets (SLC6A4, MIF, DPP4, PRF1, SERPING1, and IL6)." (PMID 35733175, 2022). "However, the relationship between these molecules has to be analyzed and further experimentally validated concerning the possible targeting of ACE2/DPP4 and FURIN/ADAM17-related factors in diseased COVID-19 patients." (PMID 33796097, 2021). "We, therefore, discuss the role of vitamin D and DPP-4 inhibitor combination therapy (VIDPP-4i) as a potential immunomodulation strategy to prevent the development and/or halt the progression of the COVID-19-induced cytokine storm, particularly in patients with diabetes and cardiovascular disease." (PMID 33906375, 2021). "In eleven COVID-19 patients, we examined the expression of ACE2, TMPRSS and other receptors and factors, such as DPP4, HMBG1 and NRP1, that might facilitate virus entry." (PMID 34112801, 2021). "Two reviews recently published have outlined the potential of DPP4 inhibition to be involved in the pathogenesis of COVID-19 rather than a therapeutic option." (PMID 33498183, 2021). "However, in the post-COVID-19 group, ACE2 mRNA expression was reduced significantly compared with controls, while DPP-4 demonstrated similar expression levels in both groups." (PMID 34200325, 2021). "Moreover, the functional receptors for COVID-19 and SARS were angiotensin-converting enzyme 2 (ACE2), while it was (dipeptidyl peptidase 4) DPP4 for MERS." (PMID 33671652, 2021). "As severe acute respiratory syndrome coronavirus 2 (SARS-CoV-2) may bind to DPP4 (or CD26), which mediates proinflammatory signals, sitagliptin might exert anti-inflammatory effects in patients with T2DM and COVID-19." (PMID 34689790, 2021). "Due to the large distribution of ACE2 and DPP4 (CD26) in the human body, SARS-CoV-2 may infect other tissues aside from the lungs, and diarrhea is a common presenting symptom in COVID-19 patients." (PMID 34682694, 2021). "Remarkably, the RBD of MERS-CoV, which is structurally similar to that of COVID-19 (20.1% sequence identity, 65% structure similarity), recognizes a different host receptor (DPP4) for its cell entry and does not bind to ACE2." (PMID 32365751, 2020). "We hypothesize that diabetic patients might be more affected by COVID-19 due to increased presence ACE2 and DPP4 mediating infection and contributing to a compromised vasculature." (PMID 32848769, 2020). "DPP4, a known receptor for MERS-CoV may also act as an entry route for SARS-CoV-2 and can contribute toward the COVID-19 related adversities." (PMID 33330620, 2020). "Whether altered DPP4 expression in the setting of hypertension, as well as of other comorbidities, contributes to SARS-CoV-2 infectivity, and COVID-19 severity is currently undetermined." (PMID 33329052, 2020). "Recently, a retrospective study involving 904 patients with DM and moderate-severe COVID-19 showed that the use of DPP4 inhibitors did not significantly affect mortality and clinical outcomes." (PMID 33584268, 2020). "Regarding COVID-19, the interaction of the SARS-CoV-2 spike glycoprotein with the human dipeptidyl peptidase-4 receptor (DPP-4/CD26) could be an important virulence factor." (PMID 32904892, 2020).
COVID-19 (continued). "Given that enzymes like DPP4 and MMP1 play critical roles in immune regulation and metabolic processes, their dysregulation in the context of viral infection could be central to the metabolic disturbances observed in COVID-19 patients." (PMID 40843809, 2025). "Beyond their metabolic effects, DPP-4 is also highly expressed on endothelial and epithelial cells in lung tissues, prompting interest in the use of DPP-4 inhibitors in various pulmonary conditions, including pulmonary fibrosis, asthma, acute lung injury, and even COVID-19 13,14." (PMID 40562805, 2025). "The molecular mechanisms triggered by the binding of the S protein to its cellular receptors, such as ACE2, TLR2/4, NRP1, DPP4, and CD147, among others, across various tissues and organs, provide valuable insights and are essential in understanding the pathophysiology of both COVID-19 and LC." (PMID 40431631, 2025). "The beneficial effects of metformin and DPP-4 inhibitors suggest that patients who are established on these antidiabetic agents should remain on their current treatment (i.e., not changed to insulin) if hospitalized for COVID-19." (PMID 39835258, 2024). "Inhibition of dipeptidyl peptidase 4 (DPP4) could suppress T-cell proliferation and IL-6 and IL-10 secretion, which regulate the immune response to COVID-19 and reduce inflammation, which has been shown to provide cardiovascular and cognitive benefits to the population." (PMID 39777148, 2024). "In general, the potential use of DPP4 as a binding target (coreceptor) for SARS-CoV-2 may provide new insights into the pathogenesis of the virus and help develop monitoring and treatment strategies to address the challenges of COVID-19." (PMID 37645223, 2023). "This outlines that the role of further speculation on the decreased serum DPP4 activity in COVID-19 pathology remains limited without a deeper understanding of a clear chain of causality." (PMID 35195023, 2022). "Circulating DPP4 enzyme activity was lower in the serum of hospitalized patients with ongoing acute SARS-CoV-2 infection compared with both plasma donors who had already recovered from acute COVID-19 and those who were never exposed to the virus." (PMID 35195023, 2022). "A significant, gradual decrease in circulating DPP4 activity occurred concurrently with worsening disease severity among hospitalized COVID-19 patients (none of them on DPP4 inhibitor), and the lowest DPP4 values occurred in the group of those who subsequently died during their hospital stay." (PMID 35195023, 2022). "The DPP4 inhibitor also improves bronchoalveolar lavage IL-6 and TNF-α levels in LPS-induced mice and attenuates lung injury, meaning direct stimulation of anti-inflammatory activity in the lungs may help ameliorate lung damage from COVID-19." (PMID 36341356, 2022). "DPP4, albumin, and LDH were significantly upregulated in the airways of patients post-COVID-19 compared with HCs, validating the observations made by Olink and confirming the presence of ongoing damage within the respiratory tracts of patients previously hospitalized for COVID-19." (PMID 35151371, 2022). "Vitamin D and DPP-4 inhibitor combination therapy (VIDPP-4i) may represent a valid therapeutic approach to ratchet down the virulence of SARS-CoV-2 and modulate the cytokine storm in COVID-19." (PMID 33906375, 2021). "Since DPP-4 in the circulation degrades GLP-1 rapidly to maintain glucose homeostasis, the use of DPP-4is may promote the anti-inflammatory effect of GLP-1 and indirectly achieve the purpose of inhibiting inflammation in patients with COVID-19." (PMID 34015003, 2021). "However, a multicenter retrospective analysis in China reported that there was no significant decrease in the occurrence of poor outcomes when using DPP4 inhibitors in COVID-19 patients with T2DM compared to non-users." (PMID 34955820, 2021).